BMAL1 (basic helix-loop-helix ARNT like 1)
Description:
Transcriptional activator which forms a core component of the circadian clock. The circadian clock, an internal time-keeping system, regulates various physiological processes through the generation of approximately 24 hour circadian rhythms in gene expression, which are translated into rhythms in metabolism and behavior. It is derived from the Latin roots 'circa' (about) and 'diem' (day) and acts as an important regulator of a wide array of physiological functions including metabolism, sleep, body temperature, blood pressure, endocrine, immune, cardiovascular, and renal function. Consists of two major components: the central clock, residing in the suprachiasmatic nucleus (SCN) of the brain, and the peripheral clocks that are present in nearly every tissue and organ system. Both the central and peripheral clocks can be reset by environmental cues, also known as Zeitgebers (German for 'timegivers'). The predominant Zeitgeber for the central clock is light, which is sensed by retina and signals directly to the SCN. The central clock entrains the peripheral clocks through neuronal and hormonal signals, body temperature and feeding-related cues, aligning all clocks with the external light/dark cycle. Circadian rhythms allow an organism to achieve temporal homeostasis with its environment at the molecular level by regulating gene expression to create a peak of protein expression once every 24 hours to control when a particular physiological process is most active with respect to the solar day. Transcription and translation of core clock components (CLOCK, NPAS2, BMAL1, BMAL2, PER1, PER2, PER3, CRY1 and CRY2) plays a critical role in rhythm generation, whereas delays imposed by post-translational modifications (PTMs) are important for determining the period (tau) of the rhythms (tau refers to the period of a rhythm and is the length, in time, of one complete cycle). A diurnal rhythm is synchronized with the day/night cycle, while the ultradian and infradian rhythms have a period shorter and longer than 24 hours, respectively. Disruptions in the circadian rhythms contribute to the pathology of cardiovascular diseases, cancer, metabolic syndromes and aging. A transcription/translation feedback loop (TTFL) forms the core of the molecular circadian clock mechanism. Transcription factors, CLOCK or NPAS2 and BMAL1 or BMAL2, form the positive limb of the feedback loop, act in the form of a heterodimer and activate the transcription of core clock genes and clock-controlled genes (involved in key metabolic processes), harboring E-box elements (5'-CACGTG-3') within their promoters. The core clock genes: PER1/2/3 and CRY1/2 which are transcriptional repressors form the negative limb of the feedback loop and interact with the CLOCK|NPAS2-BMAL1|BMAL2 heterodimer inhibiting its activity and thereby negatively regulating their own expression. This heterodimer also activates nuclear receptors NR1D1/2 and RORA/B/G, which form a second feedback loop and which activate and repress BMAL1 transcription, respectively. BMAL1 positively regulates myogenesis and negatively regulates adipogenesis via the transcriptional control of the genes of the canonical Wnt signaling pathway. Plays a role in normal pancreatic beta-cell function; regulates glucose-stimulated insulin secretion via the regulation of antioxidant genes NFE2L2/NRF2 and its targets SESN2, PRDX3, CCLC and CCLM. Negatively regulates the mTORC1 signaling pathway; regulates the expression of MTOR and DEPTOR. Controls diurnal oscillations of Ly6C inflammatory monocytes; rhythmic recruitment of the PRC2 complex imparts diurnal variation to chemokine expression that is necessary to sustain Ly6C monocyte rhythms. Regulates the expression of HSD3B2, STAR, PTGS2, CYP11A1, CYP19A1 and LHCGR in the ovary and also the genes involved in hair growth. Plays an important role in adult hippocampal neurogenesis by regulating the timely entry of neural stem/progenitor cells (NSPCs) into the cell cycle and the number of cell divisions that take place prior to cell-cycle exit. Regulates the circadian expression of CIART and KLF11. The CLOCK-BMAL1 heterodimer regulates the circadian expression of SERPINE1/PAI1, VWF, B3, CCRN4L/NOC, NAMPT, DBP, MYOD1, PPARGC1A, PPARGC1B, SIRT1, GYS2, F7, NGFR, GNRHR, BHLHE40/DEC1, ATF4, MTA1, KLF10 and also genes implicated in glucose and lipid metabolism. Promotes rhythmic chromatin opening, regulating the DNA accessibility of other transcription factors. The NPAS2-BMAL1 heterodimer positively regulates the expression of MAOA, F7 and LDHA and modulates the circadian rhythm of daytime contrast sensitivity by regulating the rhythmic expression of adenylate cyclase type 1 (ADCY1) in the retina. The preferred binding motif for the CLOCK-BMAL1 heterodimer is 5'-CACGTGA-3', which contains a flanking adenine nucleotide at the 3-prime end of the canonical 6-nucleotide E-box sequence. CLOCK specifically binds to the half-site 5'-CAC-3', while BMAL1 binds to the half-site 5'-GTGA-3'. The CLOCK-BMAL1 heterodimer also recognizes the non-canonical E-box motifs 5'-AACGTGA-3' and 5'-CATGTGA-3'. Essential for the rhythmic interaction of CLOCK with ASS1 and plays a critical role in positively regulating CLOCK-mediated acetylation of ASS1. Plays a role in protecting against lethal sepsis by limiting the expression of immune checkpoint protein CD274 in macrophages in a PKM2-dependent manner (By similarity). Regulates the diurnal rhythms of skeletal muscle metabolism via transcriptional activation of genes promoting triglyceride synthesis (DGAT2) and metabolic efficiency (COQ10B) (By similarity). (Microbial infection) Regulates SARS coronavirus-2/SARS-CoV-2 entry and replication in lung epithelial cells probably through the post-transcriptional regulation of ACE2 and interferon-stimulated gene expression.
Synonyms: bHLHe5; ARNTL; MOP3; PASD3; JAP3; ARNTL1; BMAL1c; TIC
Tractability: Small molecule: a structure with a bound ligand is known. PROTAC: UniProt records ubiquitination sites on it; ubiquitination databases record sites on it.
Gene: Protein-coding gene on chromosome 11 (13,276,647 to 13,388,048, forward strand). Ensembl gene ENSG00000133794.
Subcellular location: Nucleus; Cytoplasm; Nucleus, PML body
Subcellular location (Human Protein Atlas): Nucleoplasm; Vesicles
Pathways (Reactome):
Circadian clock: BMAL1:CLOCK,NPAS2 activates circadian expression; Expression of BMAL (ARNTL), CLOCK, and NPAS2; Phosphorylated BMAL1:CLOCK (ARNTL:CLOCK) activates expression of core clock genes; Phosphorylation and nuclear translocation of BMAL1 (ARNTL) and CLOCK; Phosphorylation of CLOCK, acetylation of BMAL1 (ARNTL) at target gene promoters; The CRY:PER:kinase complex represses transactivation by the BMAL:CLOCK (ARNTL:CLOCK) complex
Cellular responses to stimuli: Heme signaling
Gene expression (Transcription): NPAS4 regulates expression of target genes
Metabolism: PPARA activates gene expression
Gene Ontology:
Molecular function: aryl hydrocarbon receptor binding; DNA binding; DNA-binding transcription factor binding; E-box binding; Hsp90 protein binding; protein binding; sequence-specific double-stranded DNA binding; DNA-binding transcription factor activity, RNA polymerase II-specific; RNA polymerase II cis-regulatory region sequence-specific DNA binding; sequence-specific DNA binding; transcription cis-regulatory region binding; transcription coregulator activity; DNA-binding transcription factor activity; protein dimerization activity
Biological process: circadian regulation of gene expression; positive regulation of circadian rhythm; positive regulation of DNA-templated transcription; positive regulation of protein acetylation; positive regulation of transcription by RNA polymerase II; regulation of hair cycle; response to redox state; circadian rhythm; energy homeostasis; negative regulation of cold-induced thermogenesis; negative regulation of DNA-templated transcription; negative regulation of fat cell differentiation; negative regulation of nuclear receptor-mediated glucocorticoid signaling pathway; negative regulation of TOR signaling; oxidative stress-induced premature senescence; positive regulation of canonical Wnt signaling pathway; positive regulation of skeletal muscle cell differentiation; proteasome-mediated ubiquitin-dependent protein catabolic process; regulation of cell cycle; regulation of cellular senescence; regulation of DNA-templated transcription; regulation of insulin secretion; regulation of neurogenesis; regulation of transcription by RNA polymerase II; regulation of type B pancreatic cell development; and 1 more
Cellular component: CLOCK-BMAL transcription complex; nucleoplasm; nucleus; aryl hydrocarbon receptor complex; chromatin; chromatoid body; cytoplasm; PML body; transcription regulator complex
Genetic constraint (gnomAD): Loss-of-function variants: 10 observed, 67.88 expected, observed/expected ratio (o/e) 0.15, 90% interval 0.09 to 0.25. The upper end of that interval is the gene's LOEUF score, 0.25, which puts it in group 1 of 6, group 1 being the genes least tolerant of losing a copy. Missense variants: 535 observed, 820.44 expected, observed/expected ratio (o/e) 0.65, 90% interval 0.61 to 0.7. Synonymous variants: 248 observed, 286.34 expected, observed/expected ratio (o/e) 0.87, 90% interval 0.78 to 0.96.
Homologues: Orthologues: macaque ARNTL (99% identical), pig BMAL1 (99% identical), guinea pig BMAL1 (99% identical), dog BMAL1 (99% identical), mouse Bmal1 (98% identical), rabbit BMAL1 (98% identical), rat Bmal1 (98% identical), chimpanzee ARNTL (97% identical), tropical clawed frog bmal1 (87% identical), zebrafish bmal1a (86% identical), zebrafish bmal1b (85% identical), Drosophila melanogaster tgo (29% identical), and 3 more. Paralogues in human: BMAL2 (49% identical), ARNT (33% identical), ARNT2 (31% identical), CLOCK (22% identical), NPAS2 (21% identical), PASD1 (8% identical).
Diseases named in the same sentence as BMAL1 in open-access papers:
BMAL1 is named in the same sentence as 345 diseases in open-access papers, as found by Europe PMC text mining. Sharing a sentence is not in itself a finding about the gene and the disease. The quoted sentences say what the papers report.
Obesity (109 papers, 2010 to 2025). Accumulation of substantial excess body fat. "Circadian abnormalities, regulated by key clock genes such as CLOCK and BMAL1, are well-documented in depressive disorders and significantly impact metabolic processes associated with obesity." (PMID 40225722, 2025). "The deficiency of BMAL1 in adipocyte was shown to contribute to obesity, although increased Ucp1 expression levels were observed." (PMID 37293491, 2023). "For example, animals with a genetic circadian disruption, such as the mutation of CLOCK and the deletion of BMAL1, are prone to obesity and metabolic syndrome." (PMID 37293491, 2023). "The adipocyte‐specific acetylation‐mimetic mutation of PPARγ K293Q (aKQ) restrains adipose plasticity during calorie restriction and diet‐induced obesity, associated with proteolysis of a core circadian component BMAL1." (PMID 36394167, 2023). "We reported that loss of Bmal1 resulted in obesity, and chronic shiftwork induced adipose tissue expansion with inflammation." (PMID 37525228, 2023). "In humans, genetic variants of CLOCK and another core clock gene BMAL1 are associated with susceptibility to obesity and type 2 diabetes, respectively." (PMID 33676029, 2021). "Although a large proportion of BMAL1 peaks were overlapping, a number of peaks were specific to non-obese OAPs (1124), while others were unique to obese ones, indicating that obesity caused a genome-wide relocalization of BMAL1 binding." (PMID 33888702, 2021). "Deficiency of microglial Bmal1 ultimately protected mice from HFD-induced obesity and increased memory performance." (PMID 34050326, 2021). "In African Americans, the Clock rs1801260 and rs6850524 were negatively associated with the presence of obesity; Bmal1 rs11022775 reduced the risk for dyslipidemia; and the Cry2 rs2292912 increased the risk for dyslipidemia and diabetes." (PMID 34141862, 2021). "Similar patterns have been observed with other murine tissue-specific deletions; loss of Bmal1 from pancreas results in severe insulin insensitivity, while adipocyte-deficiency results in obesity and altered food intake patterns." (PMID 33255707, 2020). "Observational studies in small sample populations have shown that polymorphisms in the CLOCK gene are associated with predisposition to obesity, and that two single nucleotide polymorphisms in BMAL1 are associated with Type 2 Diabetes (T2D) and hypertension." (PMID 30935034, 2019). "Obesity has also been associated with DNA methylation status of the clock genes Clock, Bmal1, and Per2." (PMID 31671625, 2019). "BMAL1 has also been revealed as a candidate gene for susceptibility to hypertension, diabetes, and obesity, and mutations in BMAL1 have been linked to infertility and metabolic dysfunctions." (PMID 29946530, 2018). "This was noted in Bmal1 deficient mice exhibiting impaired glucose and hepatic carbohydrate metabolism as well as in Clock-mutant mice exhibiting obesity and metabolic syndrome." (PMID 25799429, 2015). "A recent study, using mice with an adipocyte-specific deletion of Bmal1, a gene encoding a core molecular clock component, found obesity and reduced numbers of polyunsaturated fatty acids in adipocyte triglycerides." (PMID 23977055, 2013). "More recently, mice with Bmal1 deficiency specifically in adipocytes were generated and found to develop obesity due to increased food intake." (PMID 23990898, 2013). "For example, genetic defects within the core clock genes Clock and Bmal1 have been associated with obesity, metabolic phenotypes, hypertension, and type 2 diabetes." (PMID 22952870, 2012). "The deletion of leptin receptors in ObRb.Bmal1 mice may have also reduced their initial susceptibility to diet-induced obesity by altering receptor activity in the intestine, potentially affecting nutrient absorption." (PMID 40714221, 2025). "Similarly, pharmacological activation of BMAL1 has been linked with improved mitochondrial function and protection against obesity caused by a HFD." (PMID 40650041, 2025).
Obesity (continued). "However, other models of clock deficiency, such as Bmal1-knockout mice, are prone to obesity, which is exacerbated by HFD, but they are protected from hyperglycemia, lipidemia, and fatty liver and fibrosis." (PMID 36787197, 2023). "Additionally, obesity causes disruption of the adipocyte clock via inhibition of PPARγ, which regulates adipogenesis and leads to the downregulation of Bmal1 and other clock genes." (PMID 37626963, 2023). "As the feeding rhythm and EE were normalized in glutamine- and methionine-treated obese mice, we wondered whether Bmal1 enhancement is linked to obesity protection." (PMID 35198059, 2022). "Similarly, genetic mutation of core clock genes such as Bmal1, Clock, and Per2 leads to a dampened rhythm of food intake, and profound susceptibility to diet-induced obesity." (PMID 34557221, 2021). "Polymorphisms of the clock genes Bmal1 and clock are associated with obesity and T2DM." (PMID 34943809, 2021). "Altogether, intestinal Bmal1 deficiency protects mice from HFD-induced obesity." (PMID 34493722, 2021). "We explored the hypothesis that decreased BMAL1 occupancy at the PER2 promoter in obesity might also be associated with changes of RNA polymerase II (RNA POLII) recruitment." (PMID 33888702, 2021). "Similarly, Bmal1 KO, Per2 KO, and Cry1 Cry2 double KO result in susceptibility to obesity and metabolic disorders." (PMID 30935034, 2019). "Moreover, loss of Bmal1 resulted in obesity with reduced muscle mass." (PMID 37525228, 2023). "Thus, intestinal clock dysfunction (Bmal1 deficiency) protects mice against HFD-induced obesity." (PMID 34493722, 2021). "In obesity, the downregulation of both Bmal1 and Fads1 leads to impaired coordination between Bmal1 and Clock, further compromising lipid metabolism regulation." (PMID 40924721, 2025). "Together, these findings highlight the role of Bmal1 in regulating chemokine signaling and metabolic adaptation under dietary stress, promoting resilience against obesity and inflammation in NE-BKO mice." (PMID 40124497, 2025). "Adipocyte-specific deletion of Bmal1 leads to obesity in mice for the disrupted food intake rhythm, whereas intestinal epithelial-specific Bmal1 deletion reduces high-fat diet-induced obesity." (PMID 40307620, 2025). "Our findings revealed key insights into the effects of obesity on circadian rhythm genes, particularly the under-expression of core genes such as Bmal1 and Clock." (PMID 40924721, 2025). "In a different study, knockdown of Bmal1 in astrocytes led to sex-specific changes in energy homeostasis and obesity." (PMID 39812780, 2025). "We now show that Bmal1 deletion in neutrophils protects against diet-induced obesity and reduces inflammatory macrophage infiltration into epididymal white adipose tissue (eWAT), despite increased food intake over 20 weeks of a high-fat diet." (PMID 40124497, 2025). "Consistently, Bmal1 deletion did protect against obesity and non-alcoholic fatty liver disease induced by a high-fat diet." (PMID 38892255, 2024). "This causes increased total body adiposity and tissue weight, highlighting the role of BMAL1 in regulating obesity‐related inflammation." (PMID 38469551, 2024). "Obesity is reliably induced in Clock and/or Bmal1 mutant mice, likely as a result of elevated levels of plasma FFAs and triglycerides." (PMID 37441501, 2023). "For example, mice with Bmal1 deleted in the intestine are less vulnerable to obesity even on a high−fat diet (HFD) but have a normal phenotype on a chow diet." (PMID 37049484, 2023). "Selective ablation of Bmal1 induces beigeing with improved glucose homeostasis, whereas its targeted overexpression attenuates thermogenic induction resulting in obesity." (PMID 36581314, 2023). "In another experiment, the effect of time-restricted feeding (TRF) on preventing obesity and metabolic syndrome was investigated in the liver of Rev-erb α/β and Bmal1 knockout mice and all organs of Cry1;Cry2 knockout mice." (PMID 37441501, 2023).